IL32 (interleukin 32)
Diseases named in the same sentence as IL32 in open-access papers (continued):
Sharing a sentence is not in itself a finding about the gene and the disease.
multiple sclerosis (2 papers, 2024 to 2025). A progressive autoimmune disorder affecting the central nervous system resulting in demyelination. "Lastly, IL-32 levels are elevated in the cerebrospinal fluid of patients with multiple sclerosis or neuro-Behcet’s disease, and a polymorphism in the IL-32 promoter has been associated with increased risk of multiple sclerosis in two independent studies." (PMID 39118084, 2024). "We found that IL-32 was upregulated in astrocytes in multiple sclerosis lesions, was likely secreted in part via exosomes, and was involved in the polarization of inflammatory reactive astrocyte states." (PMID 39118084, 2024). "Considering the human genetics data demonstrating the importance of IL-32 to the pathogenesis of multiple sclerosis, studying how astrocyte IL-32 contributes to multiple sclerosis would be a worthwhile future research direction." (PMID 39118084, 2024). "Next, given that IL-32 levels have been reported to be elevated in the cerebrospinal fluid of patients with multiple sclerosis and neuro-Behcet’s disease, we wanted to see if IL-32 was upregulated in astrocytes under neuroinflammatory conditions." (PMID 39118084, 2024). "Furthermore, we found that IL-32 was involved in the polarization of inflammatory reactive astrocyte states and was upregulated in astrocytes in multiple sclerosis lesions." (PMID 39118084, 2024). "Although cerebrospinal fluid levels of IL-32 are elevated in neuroinflammatory diseases such as multiple sclerosis, the secretion mechanism of IL-32 is not well understood, as it lacks a classical signal peptide." (PMID 39118084, 2024). "In addition to its effects on the polarization of inflammatory reactive astrocyte states, we also found that IL-32 was induced by IFN-β (an old disease-modifying treatment for multiple sclerosis), and that IL32 transcript levels were upregulated in astrocytes in various multiple sclerosis lesions." (PMID 39118084, 2024).
myelodysplastic syndrome (2 papers, 2017 to 2020). A clonal hematopoietic disorder characterized by dysplasia and ineffective hematopoiesis in one or more of the hematopoietic cell lines. "Moreover, in hematological malignancies, IL-32 is remarkably increased in patients with myelodysplastic syndrome (MDS), whereas patients with chronic myelomonocytic leukemia (CMML) have markedly reduced expression of IL-32." (PMID 29190960, 2017).
pancreatitis (2 papers, 2023 to 2025). Inflammation of the pancreas. "Patients with pancreatitis and cholangiosepsis had similar plasma IL-32 levels compared to all other patients (p = 0.765)." (PMID 40149726, 2025). "Lastly, cluster #8 (i.e., PP-4) was enriched in inflammatory and EMT-inducing markers, often associated with pancreatitis and pancreatic ductal adenocarcinoma, such as LTB, IL32, and AREG." (PMID 37649117, 2023). "Additionally, underlying conditions such as pancreatitis and cholangitis did not influence IL-32 levels." (PMID 40149726, 2025).
polymyalgia rheumatica (2 papers, 2018 to 2022). A syndrome characterized by pain, stiffness, and tenderness of the proximal muscle groups including the shoulder, pelvic girdle and the neck. "IL-32 expressed by CD8 T-cells was reported to be associated with history of Polymyalgia Rheumatica (PMR) and abnormal neutrophil count in patients with GCA." (PMID 35813204, 2022). "In CD8, IL32 was common to 5 phenotypes including Polymyalgia Rheumatica, bilateral blindness and death within 12 months." (PMID 30037347, 2018).
pulmonary fibrosis (2 papers, 2020 to 2025). Chronic progressive interstitial lung disorder characterized by the replacement of the lung tissue by connective tissue, leading to progressive dyspnea, respiratory failure, or right heart failure. "In future research efforts, we will conduct an in-depth investigation of the relevant mechanisms in an attempt to establish IL-32 as a novel target for the treatment of pulmonary fibrosis." (PMID 33097029, 2020). "Previous studies have indicated that multiple cytokines, including TGF-β1, IL-1β, TNF-α, IL-17, IL-27, IL-13, and IL-32, are overexpressed in pulmonary fibrosis." (PMID 33097029, 2020). "In addition, transgenic mice overexpressing IL-32 isoforms were characterized by increased pulmonary fibrosis or greater accumulation of abdominal white adipose tissue, confirming the identified role of the cytokine in promoting fibro-adipogenesis." (PMID 39934117, 2025).
rheumatic diseases (2 papers, 2023 to 2025). "In this narrative review, we summarize the associations between IL-32 and various rheumatic diseases, and discuss the potential role of IL-32 as a biomarker in each disease." (PMID 36875066, 2023). "In this narrative review, we summarize the associations between IL-32 and various rheumatic diseases and discuss the putative role of IL-32 as a biomarker in each disease." (PMID 36875066, 2023). "Although this progress is encouraging and could help clinicians in their clinical practice, we are still far from completely understanding the exact mechanism underlying the associations between IL-32 and each rheumatic disease." (PMID 36875066, 2023). "A number of studies have shown varying roles of IL-32 depending on the type of rheumatic diseases, indicating its different role as a putative biomarker in each disease." (PMID 36875066, 2023). "Rheumatic diseases are one of the disease groups that the role of IL-32 has been extensively studied on." (PMID 36875066, 2023). "A growing body of evidence suggests that IL-32 could be used as a possible biomarker in various rheumatic diseases." (PMID 36875066, 2023). "IL-32 has been shown to play different roles according to the type of rheumatic diseases." (PMID 36875066, 2023). "Hence, the putative role of IL-32 as a biomarker is also different in each rheumatic disease: IL-32 could serve as a biomarker for disease activity in some diseases, whereas in other diseases it could be a biomarker for certain disease manifestations." (PMID 36875066, 2023).
sarcoma (2 papers, 2013 to 2021). A usually aggressive malignant neoplasm of the soft tissue or bone. "A Cox regression analysis for IL32 expression was performed for four types of cancers: SKCM, sarcoma (SARC), pancreatic adenocarcinoma (PAAD), and liver hepatocellular carcinoma (LIHC) (p < 0.01)." (PMID 34682815, 2021).
skin inflammation (2 papers, 2022 to 2023). "Although IL32 was first identified in activated T and NK cells, current literature suggests that KC appear to be an important source of IL-32 in skin inflammation, particularly in AD." (PMID 37727785, 2023). "IL-32 could therefore be considered as a novel potential therapeutic target, particularly in AD and AA, to reduce skin inflammation." (PMID 37727785, 2023). "Overview of current publications showing roles of IL-32 in skin inflammation." (PMID 37727785, 2023). "In addition, the role of the different IL-32 isoforms in skin inflammation remains to be fully elucidated." (PMID 37727785, 2023). "In general, IL-32 is an interesting target to treat skin inflammation." (PMID 37727785, 2023). "Inhibition of IL-32 or its deactivation could be a potential approach to reduce skin inflammation." (PMID 37727785, 2023).
steatosis (2 papers, 2023 to 2024). Increased lipid within the cytoplasm of cells. "Furthermore, a positive correlation was observed between IL-32 expression and steatosis grade, and between IL-32 as well as CCL20 expression and fibrosis grade." (PMID 37686029, 2023). "Furthermore, the upregulation of IL-32 expression was observed in liver samples in parallel with histological steatosis grade." (PMID 37686029, 2023). "In summary, hepatic IL-32 and CCL20 expression is increased in MASH samples with progressed activity (intense steatosis and moderate-to-severe fibrosis), and enhanced IL-32 expression was found to be related to the PNPLA3 I148M variant." (PMID 37686029, 2023).
acute lung injury (1 paper, 2011). A condition of lung damage that is characterized by bilateral pulmonary infiltrates (pulmonary edema) rich in neutrophils, and in the absence of clinical heart failure. "• The IL-32 SNP rs12934561 is associated with an increased risk of acute lung injury (ALI) as well as the need for prolonged mechanical ventilatory support." (PMID 21649914, 2011). "Our purpose was to investigate variation within the IL-32 promoter and gene, and susceptibility to and outcomes from infection associated acute lung injury (ALI)." (PMID 21649914, 2011).
acute pyelonephritis (1 paper, 2017). "We assessed the urinary and serum levels of IL-32 in pediatric patients with acute pyelonephritis (APN) with and without renal scarring." (PMID 29134126, 2017).
arterial diseases (1 paper, 2023). "Since we had established the functional link between IL-32 and endothelial cell’s dysfunction and cytokine/chemokine production, we further aimed to investigate whether IL-32 expression in vivo might be correlated with arterial diseases." (PMID 36992409, 2023).
Autoimmunity (1 paper, 2024). The occurrence of an immune reaction against the organism's own cells or tissues. "IL-32 expression is important for pathogen clearance but detrimental in chronic inflammation, autoimmunity, and cancer." (PMID 39211051, 2024).
Blindness (1 paper, 2018). Blindness is the condition of lacking visual perception defined as a profound reduction in visual perception. "In CD8, IL32, a member of the cytokine family, was common to five phenotypes: a history of PMR, visual disturbance and raised neutrophils at T1, bilateral blindness and death within 12 months." (PMID 30037347, 2018).
breast tumor (1 paper, 2023). "The interaction of integrin three and CAF-derived interleukin 32 (IL32) at the tumor cell membrane, which enables the cross-talk between CAFs and breast tumor cells, promotes BC invasion." (PMID 37970212, 2023).
Chagas disease (1 paper, 2024). A parasitic infection caused by Trypanosoma cruzi. "Levels of IL8 and IL32 were also associated with disease control in fibroblasts infected with two different strains of T. cruzi, suggesting their relevance in the pathogenesis of Chagas disease." (PMID 38251374, 2024).
chronic pancreatitis (1 paper, 2013). A chronic inflammatory process causing damage and fibrosis of the pancreatic parenchyma. "Up-regulated IL-32 expression was also observed in the pancreatic ducts of chronic pancreatitis patients." (PMID 24705103, 2013).
colorectal tumors (1 paper, 2020). "In our cohort, IL-32 has been significantly upregulated in colorectal tumors solely at protein level." (PMID 33020452, 2020). "IL-32 protein was significantly upregulated in colorectal tumors." (PMID 33020452, 2020).
dementia (1 paper, 2025). Loss of intellectual abilities interfering with an individual's social and occupational functions. "Similarly, proteins such as MMP8, IL32, NDRG1, SMOC2, or ESM1, which have been previously reported to contribute to AD pathology, showed to be significantly increased in both MCI A + T + and AD dementia, but not in MCI A-T-, suggesting a specific AD-related signature in pEVs proteome." (PMID 41282153, 2025).
dilated cardiomyopathy (1 paper, 2022). Cardiomyopathy which is characterized by dilation and contractile dysfunction of the left and right ventricles. "Herein, we evaluated the correlation between interleukin-32 gene polymorphisms (rs12934561 and rs28372698) and the susceptibility to dilated cardiomyopathy." (PMID 36505098, 2022).
emphysema (1 paper, 2016). "Tumor necrose factor (TNF) –α, interferon-γ and various classes of interleukins as the IL-1β, IL-6, IL-8, IL-10, IL-17, IL-18, IL-32 and others are involved in the progression of emphysema." (PMID 27775634, 2016).
fungal infection (1 paper, 2023). "Our work demonstrated an association of IL-32 release with fungal infection caused by T. rubrum." (PMID 37233274, 2023).
Granuloma (1 paper, 2014). A compact, organized collection of mature mononuclear phagocytes, which may be but is not necessarily accompanied by accessory features such as necrosis. "The presence of IL-32 in giant cells in ATL granuloma suggests the involvement of this cytokine in tuberculoid granuloma that deserves further investigation." (PMID 24884781, 2014).
Graves disease (1 paper, 2019). Graves' disease is an autoimmune disorder that leads to overactivity of the thyroid gland (hyperthyroidism).It is caused by an abnormal immune system response that causes the thyroid gland to produce too much thyroid hormones. "In this study, we firstly explored the association of IL-32 with Graves' disease." (PMID 31616372, 2019).
H1N1 influenza A (1 paper, 2015). "In another report, IL-32 serum levels increased prominently in H1N1 influenza A infected patients compared to normal healthy individuals, and it was found that the antiviral activity of IL-32 is via a THP-1 cell-produced factor, transferrin." (PMID 26087456, 2015).
Helicobacter pylori (1 paper, 2014). "We investigated the expression of IL-32 and its regulation mechanism in the inflammatory response of patients with Helicobacter pylori (H. pylori) infection." (PMID 24633341, 2014). "The regulation of IL-32 expression in response to H. pylori-infection could be weakened by using neutralizing antibodies to block IL-1β and TNF-α." (PMID 24633341, 2014).
Hyperinsulinemia (1 paper, 2022). An increased concentration of insulin in the blood. "Consistent with the findings in the mouse, hyperinsulinemia increased the mRNA levels of both p21 as well as SASP factors IL8, IL18, and IL32 in IHH cells, demonstrating the pro-senescent effect of prolonged hyperinsulinemia also occurs in human liver cells." (PMID 35872305, 2022).
hypoxic-ischemic encephalopathy (1 paper, 2024). "Lastly, we found preferential colocalization of IL-32 with astrocytes in a different neuroinflammatory condition—hypoxic-ischemic encephalopathy (HIE), suggesting that IL-32 may play a role in HIE as well." (PMID 39118084, 2024).
metastasis (1 paper, 2022). The spread or migration of cancer cells from one part of the body (where they first appeared) to another. "Here, we found that IL-32 was overexpressed and positively correlated to lymph node metastasis of ESCC." (PMID 35428295, 2022).
myasthenia gravis (1 paper, 2016). Myasthenia gravis (MG) is a rare, clinically heterogeneous, autoimmune disorder of the neuromuscular junction characterized by fatigable weakness of voluntary muscles. "Another study suggested that IL-32 might be correlated with the pathogenesis or immunoregulation of myasthenia gravis." (PMID 27069296, 2016).
mycobacterial infection (1 paper, 2024). "In this study, the expression levels of IL-32 and its isomers in TPE were examined, the reasons why Mtb induced IL-32 secretion in TPE were explored, and the immunomodulatory effects of IL-32 during mycobacterial infection were highlighted." (PMID 38803498, 2024).
parasitemia (1 paper, 2022). "However, the data from this study suggest that IL-32 can be induced later in infection, which contributes to reduce clinical changes of CD, and to eliminate, at least in part, the parasites, reducing the parasitemia." (PMID 35097133, 2022).
periodontal disease (1 paper, 2020). "The biomarkers showing elevated levels in the baseline saliva of patients with periodontal disease were IL-1β, IL-4, IL-6, MMP-8, and TIMP-2, while the control group showed high levels of TNF-a, IL-10, IL-17, and IL-32." (PMID 33383828, 2020). "Biomarkers showing high levels in periodontal disease were salivary IL-1β, IL-4, IL-6, MMP-8, and tissue inhibitor of matrix metalloproteinases (TIMP)-2, and those in the controls were tumor necrosis factor (TNF)-α, IL-10, IL-17, and IL-32." (PMID 33383828, 2020).
pneumonia (1 paper, 2024). An acute, acute and chronic, or chronic inflammation focally or diffusely affecting the lung parenchyma, caused by an infection in one or both of the lungs (by bacteria, viruses, fungi, or mycoplasma.). "In addition, compared with the other groups, in the group of other diseases (including pneumonia, malignant tumors, and various other lung infections, which need to make a differential diagnosis with TB), the expression of IL-32 mRNA was the lowest (p < 0.05)." (PMID 38803498, 2024).
preeclampsia (1 paper, 2022). Preeclampsia is a hypertensive disorder of pregnancy that is characterized by new-onset hypertension with proteinuria presenting after 20 weeks of gestation, and depending on mild or severe forms may initially present with severe headache, visual disturbances, and hyperreflexia. "Another study conducted on a variety of alleles and genotypes showed that IL‐32 SNP rs4786370 may be a risk factor for preeclampsia." (PMID 34799941, 2022).
pyelonephritis (1 paper, 2017). An inflammatory process affecting the kidney. "In our study, the initial levels of serum and urinary IL-32 were not different in the children with pyelonephritis that demonstrated a tendency to develop permanent renal damage." (PMID 29134126, 2017).
respiratory failure (1 paper, 2011). The significant impairment of gas exchange within the lungs resulting in hypoxia, hypercarbia, or both, to the extent that organ tissue perfusion is severely compromised. "In a second analysis, we evaluated the association between IL-32 SNPs and days on the ventilator (DOVs), another indicator of the need for mechanical ventilation in critically ill patients with respiratory failure." (PMID 21649914, 2011).
sarcopenia (1 paper, 2026). Progressive decline in muscle mass due to aging which results in decreased functional capacity of muscles. "However, multivariate analysis showed that sarcopenia remained a more robust predictor of IL32 mRNA expression than patient gender or age as well as tumour volume." (PMID 41457346, 2026). "When analysis was restricted to male patients, the IL32/ACE1 ratio was significantly elevated in sarcopenic individuals adding further evidence of a correlation with sarcopenia independent of patient gender." (PMID 41457346, 2026).
skin infection (1 paper, 2023). An inflammatory process affecting the skin, caused by bacteria, viruses, parasites, or fungi. "In the context of skin infections, IL-32 has been shown to play a supportive role in the healing of infection-related skin lesions." (PMID 37727785, 2023). "IL-32 supports T cell mediated host defence in microbial skin infections." (PMID 37727785, 2023).
skin tumor (1 paper, 2018). "We also found that tissues from skin tumor patients showed lower levels of IL-32 compared to healthy controls." (PMID 30486830, 2018). "IL-32 expression was reduced in late stage skin tumor tissues." (PMID 30486830, 2018). "With the data analysis using a genome-wide association study (GWAS), we found that IL-32 was closely related to many cancers, and further analysis showed that IL-32 was closely associated with several genes including ITGAV and TIMP-1, which have been implicated in skin tumor development." (PMID 30486830, 2018).
stomach adenocarcinoma (1 paper, 2020). "Consistent with the results in H. pylori-infected cells and INS-GAS mice, we found that the gene levels of IL-32, RELB and SLC7A11 were significantly increased in stomach adenocarcinoma tissues compared with those in normal tissues." (PMID 32457731, 2020).
tuberculous pleurisy (1 paper, 2024). "In the present study, the production, regulation, and role of IL-32 in tuberculous pleurisy (TBP) were investigated." (PMID 38803498, 2024). "In addition, few studies have been performed on patients with tuberculous pleurisy (TBP) to evaluate the function of IL-32." (PMID 38803498, 2024).
unstable angina (1 paper, 2025). "Moreover, IL-32 levels progressively increase in patients with stable angina, unstable angina, and AMI, suggesting a correlation with disease severity." (PMID 40299461, 2025).